CD4 (CD4 molecule)
Diseases named in the same sentence as CD4 in open-access papers (continued):
Sharing a sentence is not in itself a finding about the gene and the disease.
tumor (continued). "We found that tumor-infiltrating CD4+ and CD8+ T cells in HCC patients were functionally compromised." (PMID 37188191, 2023). "The true test of their efficacy will be in their ability to reprogram the immunosuppressive features of the TIME and to sustain an immune-activating TIME that will facilitate tumor antigen presentation and the cross-priming of both CD4+ and CD8+ T cells." (PMID 37626741, 2023). "Longitudinal BLI data indicated CD4+ T cell–dependent efficacy of combined IL-6 and CTLA-4 blockade, as CD4+ T cell–depleted mice receiving therapeutic Abs had accelerated tumor growth progression compared with mice receiving only the combination therapy." (PMID 36881480, 2023). "To link tumor-targeting behavior to population phenotypes, we next differentially labelled CD4+ and CD8+ TEGs in BC PDO cocultures." (PMID 35879361, 2023). "As another means to show that peripheral blood CD4+ T cells that had been activated by bacteria and microbiota or IPdBPs recognized the same tumour antigens, we compared the TCR sequences of these two populations." (PMID 37198490, 2023). "Further assessment of frequencies and relative levels of other effector T cell populations in tumor versus STM showed a notable shift in the ratio of IFNγ+ to IL-17A+ T cell frequencies (on both CD4+ and CD8+ T cell subsets)." (PMID 38074634, 2023). "Depletion of CD4+ and/or CD8+ immune cells in mice using specific antibodies confirmed that the inhibitory effect of CCL21 on tumor growth was associated with specific T cell chemoattraction." (PMID 37185750, 2023). "The level of DDIT4 expression correlated positively with the infiltration of CD4+ T cells (Cor = 0.081, p < 0.05), neutrophils (Cor = 0.097, p < 0.01), and dendritic cells (Cor = 0.102, p < 0.01) and negatively with tumor purity (Cor = − 0.179, p < 0.001)." (PMID 37391802, 2023). "TNFR2 is highly expressed by the maximally immunosuppressive subset of CD4+Foxp3+ regulatory T cells (Tregs), especially those present in tumor microenvironment (TME)." (PMID 36865537, 2023). "In peripheral blood and tumor samples, we detected different percentages of CD4+ and CD8+ lymphocytes, monocyte and myeloid-derived suppressor cells, as well as differential expression of activation- and exhaustion-related markers." (PMID 36900156, 2023). "To test this, we purified Foxp3EGFP− CD4+ Tconv cells or Foxp3EGFP+ CD4+ Treg cells by FACS from B16-F10-tumor bearing Foxp3EGFP-DTR mice and incubated them with congenically distinct naïve CD4+ Tconv cells in vitro." (PMID 38100544, 2023). "Surprisingly, in cutaneous SCC, CD4+ T cells enhance immunosuppression, tumor development, and tumor growth." (PMID 37173918, 2023). "In contrast, other studies have reported different effects, such as increased recruitment of MDSCs, increased frequency of neutrophils, and decreased infiltration of CD4 and Tregs in various tumor models." (PMID 37505292, 2023). "We identified Nrp-1 to facilitate the migration of CD4+Foxp3+ Tregs into tumor tissues in response to VEGF." (PMID 38019895, 2023). "Achieving efficient spatiotemporal coordination of antigen cross-presentation and immune effects, BANSs induce the production of CD4+ T helper cells and cytotoxic T lymphocytes, resulting in effective tumor growth inhibition." (PMID 37024939, 2023). "The percentage of the central memory T cells in mice treated with FeMOF-based cancer vaccines, such as CD44highCD62Lhigh in CD4+ T cells, is much higher than that those treated with saline or free dLLC autologous tumor antigens." (PMID 38259474, 2023). "The ratio of CD4+ to CD8+ cells in the tumor mesenchymal tumor component was also distinct, with the high NF-κB expressers having a higher mesenchymal CD4+/CD8+ ratio." (PMID 37523561, 2023). "By contrast, the proportion of pro-tumor immune cells such as naive CD4+ T cells, activated dendritic cells, and resting NK cells were negatively correlated with the expression of several signature genes including C2, F2R, and C1QB." (PMID 37747262, 2023).
tumor (continued). "This lead was maintained and even extended after tumor rechallenge, with the cured mice maintaining significantly higher percentages of CD4+ Tem cells (11.8% ± 0.2% vs. 7.7% ± 0.2%) and CD8+ Tcm cells (18.9% ± 1.5% vs. 7.4% ± 0.2%) than the controls." (PMID 37345658, 2023). "As for infiltrating immune cells, oxaliplatin upregulated the expression of CD134 and downregulated TIM-3 of CD4+ T cells, downregulated the PD-L1 expression of DC cells, which contributed to improve the anti-tumor effect and the treatment response of ICIs." (PMID 36960067, 2023). "PCA_score was negatively correlated with tumor purity and the abundance of CD4+ T cells in LGG patients." (PMID 36649311, 2023). "In contrast, treatment with an anti-VISTA monoclonal antibody (mAb) resulted in a reduction of tumor-infiltrating MDSCs accompanied by an increase of tumor-infiltrating CD4+ and CD8+ T cells." (PMID 37795437, 2023). "On the other hand, macrophages M0, NK cells resting, and CD4+ memory activated were found to be significantly more abundant in tumor samples (p < 0.05)." (PMID 37564873, 2023). "Conversely, other immune cell types, such as regulatory CD4+ T cells and myeloid-derived suppressor cells support the growth and maintenance of the tumour, limiting anti-tumour immunity within the TME." (PMID 36183010, 2023). "Accordingly, the scRNA+TCRαβ-seq data confirmed that the expanded pre-REP TIL clonotypes mostly encompassed a CD8+ TEXH-cell phenotype in the original tumor samples, whereas the most expanded REP TIL clonotypes originate from tumor CD4+ TCYTOTOXIC cells." (PMID 37484198, 2023). "More generally, how CD4+ CAR T cells eliminate tumor cells in responsive models has yet to be fully understood." (PMID 37248395, 2023). "We extended our investigations to explore the influence of TAGAP on CD4+ T cell function, which is pivotal in orchestrating anti-tumor immune responses." (PMID 37744350, 2023). "In non‐inflamed tumors, the wide expression of S100A5 in tumor cells inhibited the infiltration of CD4+ and CD8+ T cells into the tumor region (non‐inflamed)." (PMID 37414584, 2023). "Further studies revealed that the tumor-specific augmentation is supported by NK, CD4+, and CD8+ T cells." (PMID 37251920, 2023). "The number of unique anti-tumor memory clonotypes in the peritoneum varied from 1 to 8 in CD4 and 4-8 in CD8 T-cells with a median of 4 CD4 T-cells and 6 CD8 T-cells." (PMID 37033929, 2023). "In the NE(PD1nb) group, the tumor‐infiltrating CD4+ T‐cells showed higher expression of CD69 than those in the other groups by at least threefold." (PMID 37565362, 2023). "Upon activation in response to antigen stimulation in the context of MHC class II molecules, CD4+ T cells undergo proliferation and differentiation to generate effector CD4+ T cells in the draining lymphoid tissues of the tumor." (PMID 37834375, 2023). "While the functional interplay of CD4+ memory cells directly shapes the effects of PD-L1/PD-1 inhibitors on CD8+ anti-tumor responses, the exact mechanisms mediating this response remain elusive." (PMID 37638022, 2023). "The intraperitoneal injection of SR-8314 and SR-8291 led to increased frequencies of CD4 + and CD8 + T cells and resulted in a decrease in tumor-associated macrophages in tumor-bearing mice." (PMID 37354378, 2023). "In cancer, neoantigen (NeoAg)-specific CD8+ T cells capable of direct tumor recognition have been extensively studied, whereas the role of NeoAg-specific CD4+ T cells is less well understood." (PMID 37400675, 2023). "In OC model mice, blocking TIGIT significantly reduced tumor growth and the proportion of CD4+ Tregs and increased the survival rate." (PMID 37670328, 2023). "Consistent with this, depletion of CD8+ T cells before the transfer of CD4+ T cells and tumor inoculation prevented tumor rejection." (PMID 37400675, 2023).
tumor (continued). "We confirmed the fundamental difference in the spatial distribution and migratory behaviour of CD4+ and CD8+ T cells in tumour tissues using amelanotic (Tyr-KO) MHC-deficient HCmel12 Jak1-KO tumours that express tagBFP-Ova." (PMID 37316667, 2023). "The aim of this study was to determine the prognostic significance of CD8+ and CD4+ tumor-infiltrating lymphocytes (TILs), tumoral cell PD-L1 expression, BRCA mutational status and tumor mutation burden (TMB) in early-stage HGSOC." (PMID 37446361, 2023). "Infiltration of CD8+ T cells, CD4+ T cells, NK cells and M1 macrophages kill tumor cells, whereas Treg and M2 macrophages promote tumor growth and proliferation." (PMID 37124502, 2023). "The principle of peptide cancer vaccines is based on selecting peptide sequences from either tumor-specific or tumor-associated antigens containing T cell epitopes, which are recognized by CD8+ and/or CD4+ T cells in a population with matching HLA haplotypes." (PMID 36999039, 2023). "DCs are known for their essential role in activating the anti-tumor immune response through phagocytosis and the presentation of antigens from apoptotic tumor cells to CD4+ and CD8+ T cells." (PMID 37760494, 2023). "published the spatial single- cell immunophenotyping of the tumor microenvironment of 27 NSCLC patients following ICI and found that CXCL13 expression on CD4+ T-cells was associated with good prognosis." (PMID 37901220, 2023). "In this analysis, activated CD4 memory T cells showed the second highest concordance (behind eosinophils) between primary tumor and liver metastases." (PMID 37768208, 2023). "Altogether, these data indicate an endogenous T cell response against MC38 tumours, which is characterised by increased recruitment and/or expansion of activated CD4+ and CD8+ effectors within the TME." (PMID 37153625, 2023). "Supporting this, our previous study showed an inverse association of tissue F. nucleatum abundance with tumor stromal densities of CD3+ cell and CD3+CD4+CD45RO+ cells." (PMID 37538192, 2023). "We describe a unique tumor-infiltrating immune profile with high levels of lymphocytes (CD4, FOXP3) and dendritic cells (CD21, CD1a and CD83) that are valuable prognostic factors in post-NAC TNBC patients." (PMID 36765559, 2023). "CD4 T cells are a special type of T cells targeting tumor cells in various ways, which can directly eliminate tumor cells through cytolysis, or indirectly kill tumor cells by increasing the number of B Cells and CTL (Cytotoxic T Lymphocytes) responses." (PMID 38154092, 2023). "Subsequent tumor immune infiltration analysis indicated that neutrophil infiltration, resting CD4 memory T cells, and resting natural killer (NK) cells correlated with the risk score." (PMID 38268915, 2023). "In this study, we revealed that many CD4+ CTLs infiltrate the tumor lesion together with CD8+ T cells." (PMID 38077321, 2023). "Studies using mouse models have demonstrated that diminishing CD4+ cells results in tumor rejection failure by the cellular defense system." (PMID 38328405, 2023). "Notch3 was closely related to immune infiltration (macrophages, CD4+ T cells, and dendritic cells) and tumor proliferation." (PMID 37284062, 2023). "CD4 T cells derived from tumor-regressing mice exhibited HLA-II-dependent and tumor-specific killing ex vivo." (PMID 37185301, 2023). "Dendritic cells-derived exosomes migrate to tumor cells and present antigens directly or indirectly to CD4+ and CD8+ T cells that induce an immune response." (PMID 38188673, 2023). "Significantly increased primary tumor staining for CD4, CD8α and NCR-1 as NK(-T) cell marker upon eMSC compared to sham treatment in all operated mice corroborated the flow cytometry results." (PMID 37928528, 2023). "We found that only GZMBmo/hi cell clusters (C2/10/13/4) showed high enrichment of the reported neoantigen-reactive tumor-infiltrating CD4+ and CD8+ (TILneo4 and TILneo8) GSs, suggestive of these cells being tumor-reactive CTL." (PMID 37327346, 2023).
tumor (continued). "Concurrently, CD4+ helper T cells provide the necessary support by releasing cytokines, activating other immune cells, and enhancing the anti-tumor immune response." (PMID 37376502, 2023). "CD4+ T cell engagement with antigen-presenting macrophages has also been shown to promote indirect tumor cytotoxicity of reactive oxygen species." (PMID 38063199, 2023). "Implementing CD8+ and CD4+ epitopes into cancer vaccines is predicted to safely induce an immune response that removes tumor cells expressing the same epitopes." (PMID 37513844, 2023). "Meanwhile, T cells appeared to exhibit distinct tissue distributions, with higher proportions of Treg, Teff, T-Tex, and P-Tex cells being observed in tumor tissues while more DN and CD4-Tex cells being observed in adjacent normal tissues." (PMID 36811599, 2023). "In this review, we summarize CD4+ T cells play multiple roles in tumor and chronic viral responses, including antitumor and antichronic viral roles and protumor and prochronic viral roles." (PMID 37829505, 2023). "A study has shown that a relatively high ratio of CD4 + tumor-infiltrating lymphocytes to CD8 + tumor-infiltrating lymphocytes was observed around GBM, which was proved to be a signal of poorer overall survival." (PMID 37046332, 2023). "Our study found that lipocalin-2 (LCN2) was significantly upregulated in tumor-infiltrating CD4+ T cells in CRC." (PMID 38072118, 2023). "Netrin-1 interacts with neo-genin (neonatal protein), enhances the chemotaxis of CD4 + T cells, and triggers a pro-inflammatory response, playing a key role in the regulation of the tumor microenvironment." (PMID 37568074, 2023). "CD4+ and CD8+ regulatory T cells generally suppress immune responses, and consequently, their infiltration into tumours has been linked to worsened prognoses in many forms of cancer." (PMID 37936700, 2023). "In contrary, those cells performing anti-tumor responsiveness (i.e., activated CD4 T cells, effector memory CD4 T cells, and CD8 T cells) were significantly negatively correlated ALOX5AP expression (P < 0.001)." (PMID 37994961, 2023). "In line with this, CHAC1 deficiency in tumor cells impaired the infiltrations of CD8+ T cells, and expressions of IFNγ and TNFα in CD8+ T cells and CD4+ T cells that were all induced by the combination therapy." (PMID 37553341, 2023). "Although CD8+ T lymphocytes have shown anti-cancer clinical promise, limited data have been reported on the role of human CD4+ T cell subsets in tumor immunity." (PMID 37170241, 2023). "Apart from their helper functions, CD4+ T cells can directly kill tumor cells through the release of granzyme B and perforin or by secreting effector cytokines such as tumor necrosis factor (TNF)-α or interferon (IFN)-γ." (PMID 36980536, 2023). "In tumor-draining lymph nodes, the proportion of CD4+ T cells among total T cells increased upon combination therapy, whereas the proportion of CD8+ T cells decreased." (PMID 37685868, 2023). "IFN-γ–secreting CD4+ TILs also expressed the coinhibitory marker programmed cell death 1 (PD-1), consistent with published signatures of tumor-reactive CD4+ TILs." (PMID 36512410, 2023). "The anti-tumor effects of CD4 + Th1 and pro-tumor effects of CD4 + Th2 cells have been confirmed in several studies." (PMID 37221555, 2023). "Taraxasterol regulated the immunity of H22 bearing mice by elevating the ratio of CD4+T cells in the spleen, and increasing the number of T cell infiltration in tumor tissue." (PMID 37274637, 2023). "For example, M1 polarized macrophages, activated dendritic cells (DCs), CD8+ tumor infiltrating lymphocytes (TILs), and anti-tumor helper CD4+ T cells (Th1) positively correlate with survival." (PMID 36816919, 2023). "CD4+ T cells are necessary to build a humoral response against tumor Ags by providing help via CD40 ligand signaling to CD40 on B cells to drive their differentiation and maturation into affinity-matured, class-switched plasma cells." (PMID 36719372, 2023).
tumor (continued). "In studies comparing cryoablation and RFA, although both can induce antigen-specific T lymphocyte responses, cryoablation can induce stronger antigen-specific CD4+T cells, so cryoablation has a stronger ability to induce anti-tumor immune targeting." (PMID 36761748, 2023). "Immunological changes in the spleens of tumor-bearing mice were comparable between the 2 models but the baseline frequency of regulatory T cells (CD25+FoxP3+CD4+ T cells) was higher in the EO771 model." (PMID 36757800, 2023). "Given that RNase1 increases cell frequencies of CD4+ Th1, Th17, and NK cells, it is possible that RNase1 increases CD4+ T cell-specific subsets, which in turn activate NK cell function to generate a more robust immune response for eradicating tumor cells." (PMID 37416781, 2023). "The heterogeneity of CD4+Treg offer diverse mechanisms that contribute to the modulation of anti-tumor immune responses and facilitate immune evasion." (PMID 38250084, 2023). "We did observe two tumor-free animals among anti-PD-1-treated Chatfl/fl; Cd4-cre mice, a status rarely seen for this genotype." (PMID 37640929, 2023). "A2AR and/or A2BR+ DCs showed decreased CD4+ T cell priming and anti-tumor immune responses in the TME." (PMID 37834375, 2023). "Some of these cells mediate tumor-antagonizing immune responses that suppress tumor progression, such as natural killer (NK) cells, dendritic cells (DCs), effector CD4+ T cells, and CD8+ T cells." (PMID 37834375, 2023). "An immune-enriched tumor phenotype is characterized by the presence of various TILs, including CD4- and CD8-expressing effector T cells, as well as inhibitory Tregs, myeloid-derived suppressor cells, suppressor B cells, and CAFs." (PMID 37345086, 2023). "Both CD8+ and CD4+ CAR T cells demonstrated increased infiltration into the tumor bearing compared with contralateral brain hemispheres, with greater infiltration of CD4+ T cells, supporting the flow cytometry results." (PMID 36890859, 2023). "GAL‐9 ligates with T‐cell immunoglobulin and mucin protein‐3 (TIM‐3), a cell surface inhibitory receptor found mainly on activated CTLs and CD4+ T cells, as well as PD‐1 leading to T‐cell apoptosis thereby preventing T cell‐mediated tumor cell elimination." (PMID 36751105, 2023). "Increased HLA-II expression on tumor cells, as well as increased frequencies of CD4 CTLs in the blood and tumors, are consistent with the direct tumor-killing function of CD4 CTLs." (PMID 37185301, 2023). "Reduced infiltration of neutrophils, CD4+ T cells and CSCs with tumour progression was found, accompanied by increased TAMs infiltration." (PMID 37491740, 2023). "We also observed a statistically significant increase of CD4+ T cells infiltrating the tumor with an effector memory phenotype (CD44+, CD62L-) consistent with the induction of a strong and long-lasting antitumor response." (PMID 38152397, 2023). "A comparable number of CD4 T lymphocytes per mm2 of tumor area was detected in the tumor core as well as in the tumor edge in all three tumor models." (PMID 37296466, 2023). "In a CT26 tumor model, some depletion of total CD4 cells was seen, but it was dependent simply on an intact backbone as there was no large difference between WT-TGT or SEA-TGT intratumoral cell levels and no changes were seen with LALA." (PMID 38022590, 2023). "For other CD4+ T cell subsets like Th2 and Th17, the mechanisms are still ambiguous for their both pro-tumor and anti-tumor efficacy in cancer immunity." (PMID 37508545, 2023). "The immunohistochemical profile in our study matched the pattern reported by Moon et al13 in 97 Korean patients (the majority of tumor cells were CD4 positive)." (PMID 37062543, 2023). "CD4+ or CD8+ T cells isolated from splenocytes of non–tumor-bearing mice vaccinated with PancVAX2 were cocultured with peptide pulsed bone marrow–derived DCs (BMDCs) and assessed for IFN-γ secretion by ELISpot." (PMID 38063199, 2023).